IL11 (interleukin 11)
Diseases named in the same sentence as IL11 in open-access papers (continued):
Sharing a sentence is not in itself a finding about the gene and the disease.
colon carcinoma (continued). "IHC also confirmed that IL-11+ fibroblasts expressed Wnt5a in colons affected by DSS-induced colitis and colon tumor tissues from AOM/DSS-treated mice." (PMID 33863879, 2021). "To characterize IL-11+ cells in human colon tumor samples, we collected human tumor samples, including adenoma and early and advanced CRC for IHC with anti-human IL-11 antibody." (PMID 33863879, 2021). "In line with our results, gp130 inhibition with the SERM bazedoxifene has been reported to result in a reduction of interleukin-11 induced STAT3 phosphorylation, proliferation and viability, as well as organoid and xenograft growth in colon cancer." (PMID 32940862, 2021). "IL-11 stimulation-induced phosphorylation of STAT3 in AKTP tumor organoids and human colon cancer cell lines." (PMID 33863879, 2021). "In the functional study of core down‐regulation factors, it was found that IL6, GM‐CSF, IL11, CCL3 and S100A8/9 increased the viability of colon cancer cell lines and decreased the apoptosis rate of colon cancer cells with irradiation and chemical treatment." (PMID 31650683, 2020). "In the functional study of core down‐regulation factors, it was found that IL6, GM‐CSF, IL11, CCL3 and S100A8/9 increased the viability and decreased the apoptosis rate of colon cancer cells with irradiation and chemical treatment." (PMID 31650683, 2020). "The expression of GP130, IL-11, IL-11 receptor α (IL-11Rα), IL-6, IL-6 receptor (IL-6R) and STAT3 activation were examined by western blot in DLD-1, HCT-15, and HCT-116 colon cancer cell lines." (PMID 30736824, 2019). "The IL-11/GP130/STAT3 pathway is involved in drug resistance in a variety of human cancers, including colon cancer." (PMID 30736824, 2019). "Onnis et al43 showed that IL-11 activates an oncogenic signalling pathway, through STAT1 and 3, that increased anchorage-independent growth in prostate cancer PC3, colon cancer HCT116, and renal cancer RCC4 cells." (PMID 27384883, 2016). "There is good evidence that IL-6 family cytokines (IL-11 and IL-6) and STAT3 signaling are important for the survival and proliferation of colon tumor cells in mouse models." (PMID 25890501, 2015). "In ApcMin/+ mice, Il11 and Egfp mRNA expression levels were elevated in colon tumors compared with nontumor tissues, and IL-11+ cells appeared in the stroma surrounding tumor cells in the colon." (PMID 33863879, 2021). "In contrast, only IL-11+ and not EGFP+ cells were detected in the colon tumor tissues of AOM/DSS-treated Il11-Egfp BM chimeric mice." (PMID 33863879, 2021). "Consistent with the results of DSS-induced colitis, the expression of Tgfb1-3 was not elevated in the colon in AOM/DSS-treated mice and ApcMin/+ mice, and anti-TGFβ antibody did not reduce the expression of Il11 in colon tumor tissues in these mice." (PMID 33863879, 2021). "Intriguingly, most but not all subsets of genes elevated in IL-11+ fibroblasts were significantly upregulated in colon cancer tissues relative to normal mucosa." (PMID 33863879, 2021). "Given our previous observations that IL11 signaling confers potent activation of STAT3 in gastrointestinal cancer cells, we next examined the effects of bazedoxifene on cytokine‐stimulated human gastric and colon cancer cells." (PMID 30885958, 2019). "All three colon cancer cells highly expressed GP130, IL-11, IL-11Rα and p-STAT3." (PMID 30736824, 2019). "The role of tRXRα expression in myeloid cells was also illustrated by increased macrophage infiltration and mRNA expression of IL-6, IL-11, and TNFα in colon tumor tissues from LysM-tRXRα but not in LysM-RXRα mice." (PMID 30931933, 2019). "Studies showed that TGF-β regulates the cancer stem cell self-renewal and differentiation properties via inducing leukemia inhibitory factor (LIF) and IL-11 activation of the JAK/STAT pathway and STAT3 phosphorylation in glioblastoma and colon cancer, respectively." (PMID 30944375, 2019).
colon carcinoma (continued). "After we identified the activation of GP130, IL-11, IL-11Rα and STAT3 expression in human colon cancer cells, we confirmed that the neutralized GP130 antibody could reduce the viability of human colon cancer cells." (PMID 30736824, 2019). "Since repositioning identified a novel function of bazedoxifene against interaction between IL-11 and GP130, we tested whether the inhibition mechanism was through targeting IL-11 in DLD-1 HCT-15, and HCT 116 colon cancer cells." (PMID 30736824, 2019). "IL-6 and IL-11 mRNA expression were increased in colonic tumors compared with non-tumor tissue in both Iron/DSS and Control/DSS mice (P<0.05)." (PMID 24223168, 2013). "However, IL-11, rather than IL-6, plays a more prominent role in promoting colon cancer cell growth." (PMID 30736824, 2019). "In our study, tumor epithelial cells isolated from stage II primary colon cancers, mRNA transcript expression of IL6 and IL11, their cognate receptors, and gp130 were detected although it was the expression levels of gp130 which determined cellular sensitivity to IL6 and IL11 stimulation." (PMID 30885958, 2019). "Likewise, bazedoxifene treatment of human colon cancer cells harboring mutant APC did not reduce aberrant canonical WNT signaling, but suppressed IL11‐dependent STAT3 signaling." (PMID 30885958, 2019).
colitis (24 papers, 2011 to 2025). Inflammation of the colon. "Blocking IL‐11 signaling reduces the cancer development caused by colitis in AOM/DSS‐induced CAC models." (PMID 40548181, 2025). "DSS-induced colitis model animals have been reported to have elevated levels of several proinflammatory cytokines, including IL-6 and IL-11, both of which are associated with CRC development via p-STAT3." (PMID 38504172, 2024). "In our own studies, we found that expression of IL11 in stromal cells in mice causes severe colitis and death." (PMID 38054591, 2023). "IL-11+ cells associated with colitis were also positive for vimentin, collagen I, and collagen IV, but not αSMA, suggesting that these cells were fibroblasts, but not myofibroblasts." (PMID 33863879, 2021). "In colitis-associated tumorigenesis and human CRC cohorts, heightened IL-11 signaling tracks with worse outcomes and promotes tumor cell survival by engaging STAT3—a pathway that drives target genes relevant to CRC biology, including SOCS3 and surviving." (PMID 41153383, 2025). "While most of the work on understanding the function of telocytes as it relates to fibrosis remains descriptive, a recent study using a chronic DSS murine colitis model suggests the importance of IL-11-producing fibroblasts in IBD-relevant fibrosis." (PMID 39872845, 2024). "We end by suggesting the IL11/IL33 axis as a potential therapeutic target for fibro-inflammatory diseases such as colitis, systemic sclerosis and rheumatoid arthritis." (PMID 36012165, 2022). "Conversely, a transgenic mouse model driving Il11 expression in smooth muscle cells or fibroblasts was shown to spontaneously develop colitis, as well as inflammation in other organs." (PMID 35085231, 2022). "Newer data challenge the earlier literature on the role of IL11 in inflammation as its activity in fibroblasts is now thought to promote inflammation in colitis, synovitis and cancers." (PMID 36012165, 2022). "The absolute conviction of IL11′s anti-inflammatory activity is apparent from clinical trials in which rhIL11 was administered to patients with hepatitis, colitis, rheumatoid arthritis and other conditions." (PMID 36012165, 2022). "In contrast to the results in DSS-induced colitis, we detected a few IL-11+ cells expressing epithelial cell markers, such as EpCAM and E-cadherin, in tumor tissues." (PMID 33863879, 2021). "In the colitis model, IL-11+ fibroblasts exclusively expressed stromal cell markers, such as Thy1 and podoplanin." (PMID 33863879, 2021). "The newly developed Il11-Egfp reporter mice enabled us to characterize the IL-11+ fibroblasts that appeared in mouse models of colitis and CAC." (PMID 33863879, 2021). "In this study, we generated Il11-Egfp reporter mice to characterize IL-11+ cells in different murine tumor and colitis models." (PMID 33863879, 2021). "On the other hand, blockade of the MEK/ERK pathway by trametinib attenuated Il11 expression in mouse colon in DSS-induced colitis, AOM/DSS-induced CAC, and colon adenoma in ApcMin/+ mice." (PMID 33863879, 2021). "Together, these findings suggest that colitis alone was sufficient to induce Il11 expression in fibroblasts." (PMID 33863879, 2021). "For a more detailed comparison of the phenotypes of IL-11+ fibroblasts in tumor tissues and the IL-11+ cells that appeared in colitis, we also analyzed the expression of various cell surface markers in the latter." (PMID 33863879, 2021). "On the other hand, IL-11 can improve intact intestinal barrier in mice model colitis by up-regulation of TLR-2 in the colon." (PMID 29914371, 2018). "Those that were upregulated by 1 log fold or higher include IL-9, IL-13, IL-4, IL-17A, IL-5, IL-24, IFN-γ, IL-10, IL-11, and IL-27, many of which are known cytokines involved in the pathogenesis of colitis." (PMID 21365015, 2011). "Additionally, IL‐11, which is triggered by colitis, activates STAT3 in the epithelial cells of colonic crypts." (PMID 40548181, 2025).
colitis (continued). "IL-11 is protective in ischemia–reperfusion injury, colitis, and accelerates wound healing." (PMID 39294573, 2024). "HPS patients can also suffer from colitis — perhaps an additional IL11-related pathology." (PMID 38054591, 2023). "We next investigated whether Il11 expression was induced in the tumor microenvironment in a manner similar to that in DSS-induced colitis." (PMID 33863879, 2021). "To determine whether colitis alone induces IL-11 expression, we treated Il11-Egfp reporter mice with only DSS." (PMID 33863879, 2021). "In this stage of colitis, food intake with βGh (CβGh+ group) up-regulated the expression of the Il13, Il21, Il27, and Lta genes and down-regulated the expression of the Il1a, Il11, and Il17a genes." (PMID 33923129, 2021). "In acute colitis models with severe erosion and fibrosis, such as DSS mice and IL-11 transgenic mice, substantially higher calprotectin concentration is reported." (PMID 37962942, 2024). "To further characterize the IL-11+ fibroblasts that appeared in colitis, we used a cell sorter to isolate EGFP+ and EGFP− fibroblasts from the colons of DSS-treated Il11-Egfp reporter mice and compared their gene expression profiles using RNA-seq." (PMID 33863879, 2021). "The phenotype named Colitis contains seven DEGs from our lists: IL10, IL11, IL1B, IL1RN, IL6, MIF and TNF." (PMID 34680872, 2021). "In addition, DEGs associated with the immune receptor (Lrrc19), cell chemotaxis (Ccr7, Cxcl1, Cxcl5, Cxcl9, and Cxcl10), and inflammatory response (IL1r11, IL11, Tnf, IL1β, and IL18) were also upregulated in the colonic tissue of colitis mice in DVF group." (PMID 38172943, 2024). "Together, these results are strong evidence that IL-11− cells became IL-11+ cells; alternatively, IL-11+ cells could have been recruited to tumor tissues in the absence of colitis." (PMID 33863879, 2021). "Together, these results suggest that Il11 expression was induced in a MEK/ERK-dependent manner, although the upstream signals that induce activation of the MEK/ERK pathway could differ between colitis and tumors." (PMID 33863879, 2021).
lung cancer (21 papers, 2013 to 2025). A malignant neoplasm involving the lung. "Next, we repeated attempts to assay IL-11 at even higher sensitivities, which has been gaining research traction as a diagnostic marker for lung cancer, in all three sample types: plasma, serum, and EBC." (PMID 39329890, 2024). "In support of the finding that IL11 promotes cancer pathology, multiple clinical studies have now associated IL11 to poorer prognosis in lung cancer (reviewed below)." (PMID 35883698, 2022). "Blood is one of the more readily accessible sources for biomarker discovery in the clinic, but several potential challenges exist with utilizing circulating IL11 concentrations as a diagnostic biomarker for lung cancer." (PMID 35883698, 2022). "This is consistent with previous reports that IL-6 and IL-11 expression and activated signaling pathways were positively linked with irradiation resistance in lung cancer, liver tumors, prostate cancer and leukemia." (PMID 31754344, 2019). "In addition, increased IL‐11 mRNA expression in lung cancer patients is associated with worse overall survival." (PMID 38023717, 2023). "In addition to IL-6, breast and lung cancer cells are known to rely on autocrine signaling by IL-11 for their tumor-associated functions, including survival, invasion, and metastasis." (PMID 31491838, 2019). "Previous studies have shown varying effects of the angiomodulatory effect of IL-11 on different diseases, such as rheumatoid arthritis and lung cancer." (PMID 39294742, 2024). "Lung cancer cells secrete IL-6 and IL-11, which can activate various signaling pathways such as PI3K/Akt and MAPK, promoting cell proliferation and migration." (PMID 38571500, 2024). "We show that the IL‐11 GIPR variant is an agonist cytokine that induces increased pSTAT3 signaling as compared with WT IL‐11 in the HeLa reporter cells and A549 human non‐small cell lung cancer cells (NSCLC)." (PMID 38023717, 2023). "To evaluate therapeutic efficacy more effectively in mouse lung cancer models, we sought to engineer an IL‐11 antagonist that has higher affinity for hIL‐11R and mIL‐11R." (PMID 38023717, 2023). "This alternative explanation is supported by a study that demonstrated increased IL11 protein in lung cancer tissue as quantified by ELISA." (PMID 35883698, 2022). "Treatment with CM from 4 different lung cancer cell lines for 48 h led to increased expression of Acta2, IL-6, IL-11 and LIF." (PMID 31196220, 2019). "IL-11 facilitated lung cancer cell chemoresistance to cisplatin via the IL-11R/STAT3 signaling pathway by promoting activation of the anti-apoptotic proteins Bcl-2 and Survivin in lung adenocarcinoma." (PMID 29100303, 2017). "We also investigated that IL-11 concentration in lung cancer tissue is more abundant than the normal lung tissue (**p < 0.01)." (PMID 27922075, 2016). "The results of flow cytometry demonstrated that IL-11 markedly decreased the early and later apoptosis rate of lung cancer cells induced by cisplatin." (PMID 27922075, 2016). "In the study, we found IL-11 facilitated lung cancer cell chemoresistance via IL-11R/STAT3 signaling pathway which promoted anti-apoptosis protein activation." (PMID 27922075, 2016). "Additionally, IL-11 facilitates lung cancer cell chemoresistance via the IL-11R/STAT3 signaling pathway, which promotes the activation of anti-apoptotic proteins." (PMID 40426949, 2025). "To understand whether lung cancer cells depend on IL‐11 for tumour progression, we selected two LUAD cell lines (A549, H1975) that express high levels of IL‐11 by ELISA and disrupted the IL‐11 gene by CRISPR/Cas9 technology." (PMID 40673604, 2025). "Our results agree with others, suggesting a mechanistic role of IL-11 in lung cancer." (PMID 39329890, 2024). "Unlike wild‐type IL‐11, this engineered variant potently blocks IL‐11‐mediated cell signaling and slows tumor growth in a mouse model of lung cancer." (PMID 38023717, 2023).
lung cancer (continued). "Lastly, circulating IL11 concentrations may also be affected by other pathologies unrelated to lung cancer." (PMID 35883698, 2022). "Unfortunately, IL11 protein expression in lung cancer tissue is rarely reported." (PMID 35883698, 2022). "Furthermore, another approach to identify lung cancer-treated ADSCs is detecting the secretion of IL-6 family cytokines, including IL-6, IL-11 and LIF, as initiators of the cytokine cascade that leads to STAT3 activation." (PMID 31196220, 2019). "The effect of IL-11 on decreasing apoptosis rate could be neutralized in lung cancer cells with IL-11Rα knockdown (**p < 0.01)." (PMID 27922075, 2016). "Therefore, studies in which the effect of MH or its flavonoid components is tested on cancer cells in the presence of exogenous IL-6 or IL-11 could further our understanding of the molecular targets within breast and lung cancer cells." (PMID 31491838, 2019). "However, it is as yet unclear whether IL11 plays an active role in lung cancers in IPF." (PMID 35883698, 2022). "However, IL-11 could promote colony formation capacity of lung cancer cells treated with cisplatin." (PMID 27922075, 2016). "Extracellular vesicles from lung cancer cells can activate the expression of pro-angiogenic factors, including IL-8, VEGF, LIF, oncostatin M, IL-11 and MMP 9 in adjacent stromal cells, “educating” the microenvironment to support lung cancer cell metastasis." (PMID 23908664, 2013). "We examined IL‐11/IL‐11RA axis mediated changes in the lung TME using tobacco‐induced LUAD murine models, which are immunocompetent models that better approximate the clinical reality of smoking‐related lung cancer." (PMID 40673604, 2025). "In vitro studies reveal that IL-11 can stimulate OC formation and activation, accelerate bone resorption, and release growth factors such as TGF-β in the bone matrix, thereby promoting the growth and metastasis of lung cancer cells." (PMID 38571500, 2024). "Evidence suggests that cytokines such as interleukin-1β (IL-1β), IL-6, interleukin-7 (IL-7), interleukin-8 (IL-8), interleukin-11 (IL-11), tumor necrosis factor-alpha (TNF-α), TGF-β, and C-C motif chemokine ligand 12 (CCL12) play significant roles in the bone metastasis of lung cancer." (PMID 38571500, 2024). "In bronchoalveolar lavage fluid (BALF), IL-11 levels were higher in lung adenocarcinoma (median 107 pg/mL) as compared to controls, with negative detection for IL-11 solely to be ~10 to 20% in lung cancer patients depending on the cohorts." (PMID 39329890, 2024). "For example, IL11 was detected in half of the patients with a primary lung disorder (tuberculosis, lung cancers and pneumonia) in pleural effusions but not in peripheral blood." (PMID 35883698, 2022). "Based on the UCSC Xena platform, which utilizes these datasets collectively, IL11 mRNA expression is elevated in tumor tissues as compared to adjacent normal or tissues from donors without lung cancer." (PMID 35883698, 2022). "Moreover, CAF have been validated as major source of IL-11 in tumor stroma by co-staining IL-11 and α-SMA antibodies in human lung cancer tissue section." (PMID 27922075, 2016). "Early studies involving lung cancer cells concluded that IL11 did not promote tumor cell growth." (PMID 35883698, 2022). "Hence, the use of rhIL11 on murine lung cancer is not expected to recapitulate the effect of human IL11 on human lung cancer." (PMID 35883698, 2022). "However, there was no upregulation of IL-11 mRNA expression in two lung cancer cells after treated with cisplatin for twenty-four hours." (PMID 27922075, 2016). "Furthermore, lung cancer cells with IL-11Rα knockdown showed no response to IL-11." (PMID 27922075, 2016). "The remaining six genes (IGKV4‐1, IGKV6D‐41, TNFRSF11A, INHA, IL11 and SCH3) have not been reported in the literature and may be used as potential biomarkers for lung cancer research." (PMID 32686362, 2020).